EGF (epidermal growth factor)
Diseases named in the same sentence as EGF in open-access papers (continued):
Sharing a sentence is not in itself a finding about the gene and the disease.
schizophrenia (continued). "At the early postnatal stage of rats, EGF is verified to reach the brain through the immature blood-brain barrier and promote phenotypic development of midbrain dopaminergic neurons, leading to neurobehavioral abnormalities relevant to schizophrenia." (PMID 22022452, 2011). "In addition, the role of EGF has been investigated recently in the pathophysiology of schizophrenia." (PMID 18335055, 2008). "However, it is unclear whether EGF/ErbB1 signals are enhanced or reduced in patients with schizophrenia." (PMID 36830741, 2023). "However, it remains unknown whether serum levels of epidermal growth factor (EGF) in schizophrenia are similar to those observed in the case of other neurotrophic factors." (PMID 32300175, 2020). "Thus, we speculated that abnormal expression of EGF may contribute to schizophrenia symptoms and (or) treatment efficiency." (PMID 32194452, 2020). "Our findings support the theory that lower EGF levels may lead to schizophrenia, thus lending credence to the “neurotrophic factor hypothesis” which posits that schizophrenia is the behavioral outcome of aberration in the neurotrophic factor involved in neurodevelopmental processes." (PMID 32300175, 2020). "Furthermore while perturbation to neonatal EGF signaling resulted in behavioural brain abnormalities in adulthood consistent with those present in animal models of schizophrenia, the EGF family of ligands and receptors also affect neuronal growth, differentiation and survival later in development." (PMID 24552586, 2014). "The aim of the study was to determine the serum concentration of six growth factors (EGF, VEGF, FGF-2, TGF-α, PDGF-AA, PDGF-AB/BB) in schizophrenia patients and to identify the correlations with clinical characteristics." (PMID 37185739, 2023). "Serum EGF levels and symptom severity (using the Positive and Negative Syndrome Scale (PANSS) and the Calgary Depression Scale for Schizophrenia (CDSS)) were assessed at baseline, 6-week and 6-month follow-up." (PMID 38004423, 2023). "As well in human post-mortem brain in schizophrenia, increased EGFR density was considered to offset the low EGF levels noted." (PMID 24552586, 2014). "For instance, the WNT and PI3K signaling pathways, which have been proposed to be involved in the pathophysiology of schizophrenia, are enriched in the PSD, as are the cadherin, EGF and Hedgehog signaling pathways." (PMID 23071613, 2012). "Changes in the expression levels of EGF, NRG1 and ErbBs are also found in postmortem brains and peripheral blood of schizophrenia patients." (PMID 22022452, 2011). "For schizophrenia, BDNF, Rantes and EGF gave the strongest signals, with p-values ranging approximately between 10−30 and 10−60." (PMID 20161799, 2010). "The secondary study objective was to evaluate whether EGF levels correlate with the severity of positive symptoms, overall psychopathology, total PANSS score and affective symptoms of schizophrenia and its changes." (PMID 38004423, 2023). "Initial EGF levels were not correlated with the previous clinical course of schizophrenia and its treatment (treatment duration, number of hospitalizations, antipsychotics dose), nor with cardiometabolic parameters." (PMID 38004423, 2023). "Moreover, in our preliminary study, we found a close relationship between EGF and the PANSS general psychopathology and cognitive subscore in drug-naive patients with schizophrenia." (PMID 32300175, 2020). "On the basis of a previous work, we expected that serum levels of EGF protein concentrations are abnormally low in patients with schizophrenia patients before treatment compared with control subjects, and antipsychotics or ECT brings about their beneficial effects by altering levels of EGF." (PMID 32194452, 2020).
schizophrenia (continued). "Compared to the healthy control group, serum EGF was significantly lower in patients prior to drug or combined drug + ECT treatment, in agreement with several previous reports of lower serum EGF in both acute and chronic schizophrenia patients." (PMID 32194452, 2020). "Thus, the results offer only a partial insight into the relationship between EGF and PANSS cognitive subscales in schizophrenia." (PMID 32300175, 2020). "Perinatal exposure to epidermal growth factor (EGF) induces various cognitive and behavioral abnormalities after maturation in non-human animals, and is used for animal models of schizophrenia." (PMID 31097747, 2019). "EGF and NRG1 have been researched extensively in relation to schizophrenia." (PMID 24949465, 2014). "Association of a polymorphism in EGF (one of the six EGFR ligands) with schizophrenia was reported in Finnish men, but not replicated in a Japanese population." (PMID 17598910, 2007). "Previous studies have considered the severity of all schizophrenia symptoms and have not elucidated whether EGF levels are related to the severity of positive, negative and affective dimensions." (PMID 38004423, 2023). "As secondary outcomes, we also want to evaluate possible correlations of EGF concentrations with the severity of positive dimensions, overall psychopathology, total PANSS score and affective symptoms assessed with the Calgary Depression Scale for Schizophrenia (CDSS)." (PMID 38004423, 2023). "Animal research has showed unchanged EGF levels in the brain or serum following long-term administration of typical antipsychotic agents haloperidol, which adds to the evidence that antipsychotics and ECT would not improve psychiatric symptoms via increasing EGF levels in adults with schizophrenia." (PMID 32194452, 2020). "However, no studies to date have determined whether EGF also contributes to therapeutic effect of ECT in schizophrenia." (PMID 32194452, 2020). "However, we could not find any significant changes in serum levels of EGF in patients with schizophrenia after antipsychotics alone or combined with ECT." (PMID 32194452, 2020).
cyst (33 papers, 1991 to 2025). A sac-like closed membranous structure that may be empty or contain fluid or amorphous material. "Consistent with their synergistic activities, knockdown of E(Pc) in cyst cells resulted in phenotypes resembling those caused by loss-of-function of EGF signaling pathway components." (PMID 28196077, 2017). "However, the literature does not reveal if overproliferation of the germline cells in the spi, egfr, or raf mutant animals was due to defects in germline-soma association or due to a direct requirement for EGF signaling in the cyst cells for the production of these signals." (PMID 23940622, 2013). "Inhibiting the EGF receptor (EGFR) has even been shown to decrease cystic growth in in vitro and in vivo models, suggesting that EGF signaling plays a significant role in promoting cyst development." (PMID 40801635, 2025). "At nanomolar concentrations, Sorafenib reduced ERK activity, inhibited cell proliferation stimulated by cAMP and EGF, and completely halted in vitro cyst growth in a three-dimensional collagen gel culture." (PMID 40801635, 2025). "The cyst cells fail to enclose the germline cells when animals lack signaling via the Epidermal Growth Factor (EGF)." (PMID 40700139, 2025). "Note that the primary cell culture medium used for the mammary cells contains EGF, and erlotinib treatment reduced cell proliferation as well as the size of the cysts and cyst lumens." (PMID 41132131, 2025). "In contrast to EGF and growth factor expression, the upregulation of Mcp1 precedes macrophage infiltration and promotes macrophage accumulation and cyst growth in Pkd1-knock-out mouse models." (PMID 36342644, 2023). "Treatment with 20 μM STO-609 or 10 μM W7 completely abolished the enlarged total cyst surface area per well by EGF and FSK stimulation." (PMID 36002021, 2022). "Subsequently, in primary cells isolated from ADPKD patients, epidermal growth factor (EGF) stimulated cyst formation." (PMID 34204582, 2021). "In ADPKD the concentration of EGF in cyst fluid is very low, and EGF plasma concentration as well as urinary excretion are lower in patients with ADPKD than in controls." (PMID 34206927, 2021). "As epidermal growth factor in the fluid of accumulating duct cysts has been shown to stimulate cyst growth, a similar role of PSP/REG Iα in proximal tubule cysts is anticipated." (PMID 32309450, 2020). "Cyclic AMP agonists, such as FSK, together with EGF can accelerate cyst growth by stimulating trans-epithelial Cl- secretion and proliferation." (PMID 29463793, 2018). "A significant reduction in FSK/EGF induced cyst size was observed when ADPKD cells were grown in a collagen gel." (PMID 29463793, 2018). "SAG together with FSK and EGF resulted in similar cyst number and size as FSK and EGF treatment, suggesting SAG does not exacerbate FSK and EGF-induced cyst growth." (PMID 29563577, 2018). "The EGF signaling pathway has previously been shown to control the encapsulation of germ cells by cyst cells and then regulate their proper differentiation." (PMID 28196077, 2017). "For example, the EGF signaling pathway has been shown to regulate cyst cells in encapsulating germ cells and promoting their proper differentiation in Drosophila testis." (PMID 28196077, 2017). "The treatment of EGF had a statistically significant effect on τ2 and α1MEDF in the 3D Caco-2 luminal cyst models." (PMID 28211922, 2017). "A protease called Stet acts in germ cells to cleave the Spitz (Spi) ligand to stimulate EGF signaling in cyst cells." (PMID 28196077, 2017). "We found that the EGF antagonist Yan is highly enriched in CySCs, but decreased dramatically in later stage cyst cells repressed by E(Pc) during CySC differentiation." (PMID 28196077, 2017). "Activation of EGF signaling ensures encapsulation of germ cells by the cyst cell and promotes germ cell differentiation." (PMID 28196077, 2017). "3D Caco-2 models that were untreated or treated with EGF exhibited a typical luminal cyst morphology." (PMID 28211922, 2017).
cyst (continued). "Since EGF and its related growth factors regulate the epithelial Na+ channel activity, it is possible that ENaC inhibition facilitates cyst formation in PKD." (PMID 28197498, 2016). "In our study, the cyst formation media contained 4 soluble factors and 2 signal inhibitors such as EGF, HGF, Wnt3a, R-spondin-1, ROCK inhibitor Y-27632, and TGF-β inhibitor A-8301." (PMID 27335264, 2016). "When we increased EGF signaling in testes, the germline cells also appeared properly enclosed by cyst cells but the cysts entered terminal differentiation before the germline cells completed all four rounds of TA-divisions." (PMID 23940622, 2013). "This is not surprising as the germline cells are completely enclosed by cyst cells and EGF thus cannot diffuse outside the cysts." (PMID 23940622, 2013). "Reduction in EGF signaling led to the accumulation of cyst cell-enclosed, tumor-like aggregates of early-stage germline cells." (PMID 23940622, 2013). "We conclude that the doses of EGF signaling are controlled at the level of both the active ligand produced by the germline cells and the available receptor molecules on the cyst cells as these two cell lineages develop." (PMID 23940622, 2013). "Soon after the posterior localisation of the oocyte in the D.melanogaster cyst, EGF signalling takes place in the posterior betweenthe oocyte (Grk ligand) and the overlying follicle cells (Torpedo receptor), further consolidating AP polarity." (PMID 23622113, 2013). "When we reduced EGF signaling in testes, the germline cells appeared to be properly enclosed by cyst cells but were trapped in TA-divisions." (PMID 23940622, 2013). "Here we propose that a temporal increase in EGF signaling between germline cells and surrounding cyst cells regulates cyst development." (PMID 23940622, 2013). "We propose that different doses of EGF signaling are created by the coordinated increase of EGF signaling components in the germline cells and the cyst cells as they mature." (PMID 23940622, 2013). "In summary, our data strongly support the idea that EGF signaling between germline cells and cyst cells increases as they transition from early to later stages of development, and that this increase guides early steps of gametogenesis." (PMID 23940622, 2013). "We propose that EGF signaling normally regulates a return mechanism from the cyst cells that reduces stem cell characteristics in the spermatogonia which, in turn, promotes the progression of the spermatogonia through TA-divisions." (PMID 23940622, 2013). "In this study, we used a combination of bioinformatics and molecular approaches to identify new cyst structural proteins from G. lamblia and found a group of Epidermal Growth Factor (EGF)-like Repeats containing Cyst Proteins (EGFCPs)." (PMID 20485485, 2010). "Notably, extrusion was significantly reduced in our mammary cysts upon addition of erlotinib, although the inhibitor also reduced cyst growth: EGF is present in the culture medium for primary cells and EGF ligands are needed for mammary gland development." (PMID 41132131, 2025). "Additionally, the aberrant activation of epidermal growth factor (EGF) and its receptor (EGFR) signalling has been linked to cyst expansion." (PMID 39796576, 2024). "Finally, an experimental study has shown that EGF administration ameliorated cyst progression in PKD mice." (PMID 36914219, 2023). "EGF protein is highly expressed in cyst epithelia of ADPKD patients, and primary cultures of cyst epithelia are hyperesponsive to mitogenic stimulation by EGF, which may indicate that EGF plays a role in promoting cyst formation." (PMID 31488014, 2019). "In addition, the EGF signaling pathway has been shown to control cyst cells to encapsulate germ cells and allow for their proper differentiation." (PMID 28196077, 2017). "Therefore, to further understand how E(Pc) regulates EGF signaling, we characterized the expression level and localization of dpERK in E(Pc) knockdown cyst cells." (PMID 28196077, 2017).
cyst (continued). "We discovered that EGF signaling has a dose-dependent effect on cyst development." (PMID 23940622, 2013). "We previously showed that EGF signaling regulates cyst formation." (PMID 23940622, 2013). "Thus, their appearance in the testes of cyst cell-sSpi/EGFR-animals shifted to 29°C was specifically due to the increase in EGF signaling." (PMID 23940622, 2013). "However, how EGF signaling from the germline to the cyst cells ties into germline-intrinsic activities of Bam and Nup98-96 is yet to be explored." (PMID 23940622, 2013). "To address whether and how EGF signaling plays a role in cyst development past the enclosure event, we first generated testes in which we decreased EGF signaling and investigated the resulting effect on the cysts." (PMID 23940622, 2013). "This confirms that the mutant phenotype was due to increased EGF signaling in cyst cells." (PMID 23940622, 2013). "More likely than having a direct effect on fusome morphology, we hypothesize that EGF signaling regulates a return signal from the cyst cells to the germline cells that promotes synchronous cell divisions." (PMID 23940622, 2013). "We propose that as the cysts develop, a temporal signature of EGF signaling is created by the coordinated increase of both the production of active ligands by the germline cells and the amount of available receptor molecules on the cyst cells." (PMID 23940622, 2013). "Moreover, genes of the Epidermal Growth Factor (EGF) signaling pathway may be directly regulated by the H3K27me3 methyltransferase Enhancer of zestes [E(z)] in cyst cells, to ensure proper germ cell identity." (PMID 38405894, 2024). "Finally, the EGF signaling is important for cyst cell differentiation and germline maintenance and differentiation, which regulates encapsulation of germ cells by the cyst cells." (PMID 39007366, 2024). "Furthermore, it has been reported that in 3D Matrigel culture, MDCK cells depleted of the small GTPase Arf6 form an inverted cyst, whose inversion is restored by epidermal growth factor‐elicited Rac1 activation and by expression of a constitutively active form of Rac1." (PMID 39377417, 2024). "Moreover, genes of the EGF signaling pathway might be directly regulated by the H3K27me3 methyltransferase Enhancer of Zeste [E(z)] in cyst cells to promote germ cell differentiation." (PMID 28196077, 2017). "In addition to the previously reported requirement for EGF signaling in cyst formation, a low dose of EGF signaling is required for the progression of the germline cells through transit amplifying divisions, and a high dose of EGF signaling promotes terminal differentiation." (PMID 23940622, 2013). "We present genetic evidence that a low dose of EGF signaling is required for the early stages of germline development, the progression of the germline cells through TA-divisions, and that a high dose of EGF signaling promotes the entry of germline and cyst cells into terminal differentiation." (PMID 23940622, 2013). "Furthermore; a variety of growth factors, such as epidermal growth factor (EGF), contribute to cystogenesis in ADPKD through stimulation of the proliferation of collecting duct cells, which are involved in cyst formation in ADPKD." (PMID 40801635, 2025). "The role of EGF/EGFR appears to also depend on the postnatal developmental stage because in neonatal ARPKD mice, EGF treatment did not reduce cyst expansion and also caused early death." (PMID 34650051, 2021). "These micrographs depict the value and change of α1MEDF of untreated 3D Caco-2 luminal cyst models with and without EGF treatment." (PMID 28211922, 2017). "Further, epidermal growth factor (EGF) signaling play a major role in renal electrolyte homeostasis and cyst growth in both ADPKD and ARPKD through cellular proliferation of incompletely differentiated epithelial cells and accumulation of fluid within the cysts." (PMID 28197498, 2016).
cyst (continued). "Terminal differentiation was promoted in testes expressing a constitutively active EGF Receptor (EGFR) and in testes expressing both a secreted EGF and the EGFR in the cyst cells, but not in testes expressing either only EGF or only EGFR." (PMID 23940622, 2013). "Although EGF does not seem to be an important growth factor contributing to cyst growth in ADPKD, it is still not completely clarified whether the same holds for HB-EGF." (PMID 36914219, 2023). "DAPT alone did not influence cyst formation or growth, however in combination with FSK and EGF (agonists), decreased the surface area of FSK/EGF-induced ADPKD cysts (p < 0.01), demonstrating that Notch inhibition suppresses cell proliferation and/or chloride-dependent fluid secretion." (PMID 29463793, 2018).